CTNNB1 (catenin beta 1)
Diseases named in the same sentence as CTNNB1 in open-access papers (continued):
Sharing a sentence is not in itself a finding about the gene and the disease.
tumor (continued). "The results showed that BCL2, APC, TCF, WNT, AXIN, and CTNNB1 (p < 0.05) were significantly higher expressed in tumor tissues compared to adjacent healthy tissues, and BAX was higher in control tissues than tumor tissues (p < 0.05)." (PMID 37644520, 2023). "Here, our findings showed APC, TCF, WNT, AXIN, and CTNNB1 genes were overexpressed in tumor tissues in comparison to the adjacent normal tissues." (PMID 37644520, 2023). "Consistently, stable transfection of sh‐circ‐CTNNB1 resulted in a significant inhibition in the tumour growth of xenografts formed by subcutaneous injection of 143B cells into athymic nude mice." (PMID 36181462, 2023). "Four target sequences had been previously detected in tumor DNA by standard-of-care (SNVs in either the CTNNB1, SMO, or KDM6A genes)." (PMID 37046633, 2023). "We suggest that LTB4R2 activation by 12-HHTrE produced by aHSC CYP1B1 causes CTNNB1 activation via GSK3β pathway and subsequent YAP1 transcription and tumor promotion." (PMID 37156770, 2023). "Accordingly, as compared with subcutaneous tumor cells, CTNNB1 mRNA was significantly up-regulated while RBM3 protein was significantly down-regulated in cancer cells growing in bone, which was consistent with our in vitro observations (see Result 2)." (PMID 36750551, 2023). "Martinez-Barbera showed that the CTNNB1 mutation occurs only in SOX2+ pituitary tumoral stem cells which represent the “true” tumoral cells and lead to the tumor development in a paracrine manner." (PMID 36979325, 2023). "On the one hand, CTNNB1 promotes tumor development and progression through Survivin, which inhibits apoptosis, promotes cell cycle progression, and enhances angiogenesis." (PMID 37033970, 2023). "In this study, we confirmed that upregulated circ‐CTNNB1 exerted an oncogenic role in OS tumour progression in a RBM15‐dependent manner." (PMID 36181462, 2023). "Further RT-PCR analysis followed by Sanger sequencing revealed that in total 8 out of 18 (~ 44%) tumours presented Ctnnb1 transcripts with exon 3 exclusion." (PMID 37907668, 2023). "Tumor forming analysis verified that HCG11 expression was negatively associated with miR-1276 and had a positive relation with CTNNB1 in GC mice models." (PMID 37386429, 2023). "The activation of the Wnt/β-catenin pathway by CTNNB1 mutations contributes to a decline in TIL by inducing downregulation of the chemokines CCL4 and CCL5 that attract dendritic cells and T cells into tumor tissue." (PMID 37190307, 2023). "The role and regulatory mechanism of CTNNB1 as a tumor marker in various cancers have also been reported by a number of studies." (PMID 35865532, 2022). "While spatial profiling is advantageous in differentiating the tumor landscape, the identification of T-cell exclusion and intratumor CTNNB1 expression was only possible due to the inclusion of regions both in and surrounding the tumor." (PMID 35264439, 2022). "Of note, tumour from patient 10 with biallelic mutation in PTEN and activating mutation in Wnt pathway, CTNNB1, presented the lowest density of CD3+ and CD8+ cells of the entire cohort." (PMID 36613564, 2022).
tumor (continued). "Regions of the metastasis clustered based on their presence within the tumor bed versus the invasive margin, and we identified increased expression of CTNNB1 within the metastasis tumor bed." (PMID 35264439, 2022). "E.g., combining CTNNB1 mutations and high density of CD8+ T-lymphocytes in tumor center yielded HRs of 0.12 (0.03–0.52), p = 0.005 for TTR and 0.25 (0.09–0.74), p = 0.01 for DFS." (PMID 35962322, 2022). "Among them, IGF1R and EGFR can activate PI3K/AKT and MEK/ERK signaling pathways, respectively, to enhance tumor progression and drug resistance, and YY1 activates Wnt/β-catenin signaling by promoting CTNNB1 expression to promote tumor growth." (PMID 36131281, 2022). "Our differential expression analysis revealed that the (m)RNA expression levels of DPP4/CTNNB1/MET were higher in THCA tumor tissues compared with adjacent normal tissues." (PMID 35205190, 2022). "We also verified that CTNNB1 3′ SP is conserved in mouse and is more highly expressed in the mouse tumour relative to the adjacent normal tissue." (PMID 35618746, 2022). "CTNNB1 is consistently upregulated in HB tumor cells and, when knocked down, reduces their viability and induces apoptosis." (PMID 35563821, 2022). "CTNNB1 which is involved in the beta-catenin signaling pathway usually inhibits immunity response of tumor microenvironment." (PMID 35155577, 2022). "CTNNB1 binds directly various transcription factors, which are important for tumor progression including JUN, FOSL1, SRY box transcription factor 17 (SOX17), TCF3, TCF4, and TCF7." (PMID 36457029, 2022). "Among more frequent genetic mutations in EC are alterations in the catenin beta-1 or β-catenin (CTNNB1) gene, occurring in approximately 20-25% of tumours." (PMID 35531470, 2022). "Together with mutations in the CTNNB1 and AMER1 (WTX) tumor suppressor genes, it unfolds its tumorigenic role by upregulation of the Wnt/beta-catenin pathway." (PMID 35911825, 2022). "While overexpression of Nras and Ctnnb1 promoted tumorigenesis in the mouse liver, knockdown of Smyd5 suppressed tumor formation." (PMID 35680905, 2022). "We showed that over-splicing of the CTNNB1 3′ UTR was significantly associated with the upregulation of WNT signalling and cell cycle genes in both TCGA-LIHC and PLANet tumour samples." (PMID 35618746, 2022). "Among the ten c3USPs with the highest number of over-spliced tumour samples, the top candidate, CTNNB1 c3USP (3′ SP), was over-spliced in ~40% of tumour samples (2,251/5,577) in 10 of the 11 cancer types analysed." (PMID 35618746, 2022). "The positive association between the expression of DDR1 with genes SOX9, CTNNB1, or VANGL2 emphasizes its role in stemness and tumor aggressivity." (PMID 35664781, 2022). "More frequent mutations in CTNNB1 (1.5%), AXIN1 (4%), and APC (2%) genes have been described in this tumor." (PMID 35454818, 2022). "It is therefore unlikely that CTNNB1 is sufficient as a tumor‐driver in PTCL, and other genetic or epigenetic alterations are likely involved in lymphomagenesis." (PMID 35510955, 2022). "Mutations in CTNNB1 (B) and KRAS (K) were assigned to tumor samples with a non-synonymous mutation and/or CNV gain for a given gene." (PMID 36457077, 2022). "We next measured the tumour expression of genes that were over- or under-expressed in the previously reported CTNNB1-transcriptomic signature from HCC33." (PMID 35301339, 2022). "We queried the association between the mRNA expression levels of DPP4/CTNNB1/MET and tumor infiltrations of immunosuppressive cells using the TCGA cohorts." (PMID 35205190, 2022).
tumor (continued). "To validate their expressions, we used the UALCAN online bioinformatics tool with default settings, which showed that mRNA levels of DPP4/CTNNB1/MET were higher in THCA tumor tissues compared with adjacent normal tissues." (PMID 35205190, 2022). "Two tumor specimens harbored two different mutations for each of the APC and CTNNB1 genes (subjects 6 and 37, respectively)." (PMID 34986841, 2022). "A genetic analysis of the primary tumor using the Oncomine Dx target test multi-CDx system revealed positivity for EGFR (L858R and E709X) and CTNNB1 mutations." (PMID 36519636, 2022). "Tumor cells need to switch from high-CTNNB1, low WNT5A to low-CTNNB1, high WNT5A to initiate metastasis and move away from the primary site." (PMID 36620565, 2022). "Regarding HCC, a catenin beta 1 (CTNNB1)-activating mutation is frequently observed and reported to flourish in an immune-desert tumor microenvironment, partly via C-C motif chemokine ligand 5 (CCL5) downregulation." (PMID 35884434, 2022). "CTNNB1 status can be used to stratify FIGO stage I tumours into group with a favourable prognosis (CTNNB1-wild type, with a similar prognosis to POLEmut tumors) and group with an unfavourable prognosis (CTNNB1-mutant, with a similar prognosis to MMRd)." (PMID 35531470, 2022). "In the remaining seven samples, a wildtype sequence of CTNNB1 was identified either exclusively in the tumor tissue (n = 3) or in the tumor tissue and normal tissue (n = 4)." (PMID 34885050, 2021). "Actually, miR-214 and CTNNB1 were respectively reported as having tumor suppressive and oncogenic roles in OSCC." (PMID 34268119, 2021). "At 21 days post Ctnnb1 recombination, lineage tracing in tumours was initiated by RDrePr induction and mice were then aged until maximum tumour burden, 13 days (n=2), 17 days (n=1) and 19 days (n=1) days post Ru486 induction." (PMID 33093165, 2021). "In other words, mean CTNNB1 mRNA expression was lower in the tumour subset with high CDKN1A expression than in the tumour subset with low CDKN1A expression, which was consistent with β-catenin having an inhibitory effect on CDKN1A mRNA expression." (PMID 34389725, 2021). "We next checked if the pathways we identified were also altered in female Ctnnb1 mutant tumours, compared to males of the same genotype, as these tumours shared a large number of altered genes with male double mutants." (PMID 33214683, 2021). "In uterine leiomyomas, CTNNB1 mutant cell sends the paracrine mitogenic signal to adjacent tumor cells and facilitates tumor cell proliferation." (PMID 34922552, 2021). "As expected, adrenals from Ctnnb1 mutant mice showed tumour formation characterised by increased organ size, which was larger in the female." (PMID 33214683, 2021). "Comparative analysis of the differentially expressed genes between double mutants and Ctnnb1 mutant female and male tumours showed very few common genes altered in both sexes (three genes upregulated, and six genes downregulated in both females and males)." (PMID 33214683, 2021). "In contrast, in the case of TSGs (i.e., CDKN2A, CTNNB1, and SPOP), MSCs were small and the differences between “mutation-tumor type” combinations are also small." (PMID 34424899, 2021). "In the multivariate analysis, only CTNNB1 exon 3 mutation and FIGO stage ≥ IB appeared to be independently and significantly associated with tumour recurrence (p = 0.017 and p = 0.020, respectively)." (PMID 34420090, 2021).
tumor (continued). "CTNNB1 plays an important role in tumour cells adhesion and maintains them together via controlling the cell growth and adhesion between cells." (PMID 33073304, 2021). "Here, AhCreErt was used to induce Ctnnb1 recombination and tumour initiation, and DrePr was used to trace clones derived from single cells within nascent and established tumours." (PMID 33093165, 2021). "Gene set enrichment analysis of the RNA-seq data from male Ctnnb1 and double-mutant tumours revealed enrichment in cell cycle genes in tumours with elevated Hoxb9, consistent with the increase in proliferation in double mutants." (PMID 33214683, 2021). "In our study, CTNNB1 mRNA level decreased in tumor tissues compared to the control group, while it increased in peripheral blood samples." (PMID 33237662, 2021). "This tumor sub-type showed significant overlap with both the Hoshida S3 class and the Chiang CTNNB1-activated class that were characterized by high tumor FCH uptake in our studies." (PMID 33553649, 2021). "In this study, we reviewed 85 cases of pathologically diagnosed DF and performed β-catenin immunohistochemical staining and CTNNB1 gene sequencing on tumour samples." (PMID 33914771, 2021). "CTNNB1 mutated HCC can be identified by EOB-MRI, which shows a high intensity tumor in the hepatobiliary-phase." (PMID 34201284, 2021). "Our immuno-molecular classification scheme supplemented with NSMP tumor sub-grouping based on the ARID1A and CTNNB1 status granted a more reliable risk assessment and it resulted to be particularly informative in the group of high-risk patients." (PMID 33668727, 2021). "It is essentially a dual tumor with a component of classical PTC with malignant epithelial proliferation (BRAF-mutated) and another component of mesenchymal proliferation (CTNNB1-mutated)." (PMID 34503292, 2021). "CTNNB1 mutated HCC is able to be recognized by EOB MRI, which shows high intensity tumor in the hepatobiliary phase." (PMID 34201284, 2021). "Of note, the CTNNB1 mutation was frequently detected in ACC, suggesting its possible contribution to tumor growth or progression." (PMID 34440096, 2021). "As reported from existing studies, CTNNB1 mutations occur in nearly 19%-26% of LIHC patients, capable of activating Wnt-β-catenia signaling pathway and promoting tumor progression." (PMID 34839280, 2021). "Among all the genes reported in the literature with their potential cause in tumor development, CPEB4, APC, TRIP13, EIF2S3, EIF4A1, IFNg, PIK3CA and CTNNB1 have particularly been identified to be a set of potential candidates for tumor development." (PMID 33237662, 2021). "Here our data show that increased CTNNB1 expression in tumor tissues is correlated with poor prognosis in NSCLC patients." (PMID 34465343, 2021). "It thereby acts as a protein kinase and interacts with many tumor-associated genes to accelerate carcinogenesis including HIF1α, Oct-4, STAT3 and CTNNB1 that encode β-catenin." (PMID 33652661, 2021). "CTNNB1 has been demonstrated to be oncogenic in several tumor types and its expression is regulated by multiple Wnt molecules." (PMID 34465343, 2021). "HepG2 has a large in-frame deletion in the CTNNB1 gene comprising 116 codons of exons 3 and 4 and a mutation of the TERT promoter and represents the fetal tumor subtype with high GLUL expression and GS abundance." (PMID 34235580, 2021).
tumor (continued). "Tumours with both nuclear beta-catenin and nuclear LEF1 protein expression were significantly associated with CTNNB1 mutation." (PMID 34420090, 2021). "As a result, elevated CTNNB1 expression continuously activates the Wnt/β-catenin signaling pathway, thereby promoting downstream gene expression and tumor progression." (PMID 34465343, 2021). "Recently, it has also been suggested that miRNA-423 is capable of promoting tumor cell proliferation and migration by enhancing Wnt/CTNNB1 activity, thereby inducing ZFP36 down-regulation." (PMID 32784485, 2020). "Although CTNNB1 is an essential regulator of tumor processes, our study provides the first evidence that its mRNA stability and protein expression are regulated by a circRNA." (PMID 33268793, 2020). "This tumor carried the highest number of somatic mutations herein detected, including CX3CL1 and CTNNB1 mutations, and its chromosome copy number profile was complex compared to the HB group (data not shown)." (PMID 32432034, 2020). "Among the top pathways, including 31 activated in at least four tumor types, we observed a strong impact of CTNNB1 as well as several other pathways described in the literature as influencing anti-tumor immunity such as MYC, PPARG and SHH (sonic hedgehog)." (PMID 33106165, 2020). "Private subclonal SNV and INDELs, including pathogenic CTNNB1 and PTEN mutations, existed in 6/6 (100%) of our samples, also consistent with prior multiregion sequencing in other tumor types." (PMID 32158697, 2020). "Intriguingly, the analysis showed that ASPH has considerable positive correlations in mRNA expression with GSK3B and CTNNB1 in most of normal/tumor tissues." (PMID 33015050, 2020). "This study further demonstrated regulation of Yap-1 levels by β-Catenin at the transcriptional level, and the in vivo findings strongly showed the synergistic effect that mutant CTNNB1 and Yap-1 dual activation had on HB tumor growth." (PMID 31979130, 2020). "In a recent study, 16 HBs were included in a Pan-Cancer cohort of pediatric tumors, with the identification of CTNNB1 and TERT, genes already known to be frequently mutated in this type of tumor." (PMID 32432034, 2020). "Immunohistochemical staining of xenograft tumor tissues indicated that tumor tissues from mice in the si-circXPO1 group contained fewer CTNNB1- and cyclin D1-positive cells than those from mice in the negative control group." (PMID 33268793, 2020). "Having established the molecular ground truth, we segregated tumour samples in the discovery cohort into LD (RSPO-fusions, RSPO-high and RNF43 mutations, n=64) and LI (APC or CTNNB1 mutations, n=347) subsets." (PMID 31563876, 2020). "It has been reported that high levels of Catenin Beta 1 (CTNNB1) lead to high tumor grade and poor prognosis in BC patients." (PMID 32796696, 2020). "The 7 CTNNB1 mutated MSI-H CRCs included 3 tumors analysed for LS diagnostics and one metastasized tumor from an LS patient analysed for companion diagnostics." (PMID 33115416, 2020). "In conclusion, we identified miR-142-3p exerts its function as a tumor suppressor through blocking the activation of Wnt signaling by directly targeting to CTNNB1." (PMID 33643894, 2020). "We performed a drug-repurposing screen in cell lines derived from aggressive tumours developed in Pbcre Ctnnb1(ex3Δ)/+Ptenfl/+ and PbCre Spry2fl/+Ptenfl/fl mice (CP2 and SP1 cells, respectively)." (PMID 31844184, 2020).